CDK5 (cyclin dependent kinase 5)
Diseases named in the same sentence as CDK5 in open-access papers (continued):
Sharing a sentence is not in itself a finding about the gene and the disease.
Obesity (36 papers, 2012 to 2025). Accumulation of substantial excess body fat. "While TGFB1 inhibits ASPC commitment to adipocytes, CDK5 has been associated with dysregulated PPARγ signaling in obesity." (PMID 40975767, 2025). "Phosphorylation of Ser273 in PPARγ by CDK5 (cyclin-dependent kinase 5) is associated with obesity and insulin resistance and this finding spurred research toward developing small molecules to inhibit this modification." (PMID 37893070, 2023). "When obesity was induced by a high-fat diet, CDK5 and its associated PPARγ phosphorylation were upregulated in vivo, which led to impaired insulin sensitivity." (PMID 32054125, 2020). "The researchers discovered that Gleevec blocks CDK5-mediated PPARγ phosphorylation, and thus lowers the level insulin resistance and reduces the risk of hyperglycemia and obesity." (PMID 29385209, 2018). "Obesity is associated with elevated CDK5 activity, and resulting constitutive PPAR-γ phosphorylation and reduced activity contribute to impaired adipocyte maturation and reduced adiponectin secretion." (PMID 29535807, 2018). "Moreover, It was known that Cdk5-mediated phosphorylation of PPARγ at Ser-273 was obesity-linked phosphorylation site." (PMID 32190280, 2020). "Furthermore, some dysregulated genes associated with obesity were correctly regulated by chelerythrine, including adiponectin and adipsin, which are dysregulated downstream of CDK5-mediated PPARγ phosphorylation." (PMID 26183621, 2015). "Phosphorylation of PPARγ at Ser273 by cyclin-dependent kinase 5 (Cdk5) was recently linked to obesity, and anti-diabetic PPARγ ligands (e.g. the thiazolidinedione rosiglitazone) were shown to inhibit the Cdk5-mediated phosphorylation of PPARγ in adipose tissue." (PMID 25083916, 2014). "In addition to their capacity to enhance the transcriptional activity of PPARγ, PPARγ agonists have a separable biochemical activity, blocking the obesity-linked phosphorylation of PPARγ at Ser-273 by Cdk5." (PMID 24454336, 2013). "We also found that p-F11 inhibits obesity-linked phosphorylation of PPARγ at Ser-273 by Cdk5." (PMID 24454336, 2013). "In the context of obesity, a high-fat diet activates cyclin-dependent kinase 5 (CDK5), leading to an upsurge in the phosphorylation of PPARγ at ser273." (PMID 38254542, 2024). "Serine 273 phosphorylation of PPARγ, which was shown to play a critical role in obesity and insulin resistance, is mediated by the Cdk5/ERK1/2 axis." (PMID 37047128, 2023). "Mediated by the cyclin-dependent kinase 5 (CDK5), phosphorylation of PPARγ can significantly reduce insulin sensitivity and induce obesity." (PMID 36551260, 2022). "Mechanistically, IL-17A induces phosphorylation of the serine 273 site of PPARγ in adipocytes in a Cyclin-dependent Kinase 5 (CDK5)-dependent manner, which subsequently modifies the expression of obesity-associated genes." (PMID 35574038, 2022). "Cdk5 was the initial candidate for phosphorylating Ser273 of PPARγ based on the observation that in obesity, increased expression of Cdk5 was observed in adipose tissue, as well as higher levels of pPPARγ." (PMID 34339734, 2021). "In obesity, phosphorylation of PPARγ on the Ser273 residue by CDK5 leads to dysregulation of a specific gene set." (PMID 32024237, 2020). "To investigate the possible mechanism of AMPK-mediated protective effects of crocin against obesity and type 2 diabetes, we evaluated the changes of CDK5/PPARγ signaling." (PMID 32596392, 2020). "In obesity, phosphorylation of PPARγ at Ser273 (pSer273) by cyclin-dependent kinase 5 (CDK5)/extracellular signal-regulated kinase (ERK) orchestrates diabetic gene reprogramming via dysregulation of specific gene expression." (PMID 32024237, 2020). "Phosphorylation at this site is believed to be mediated by Cdk5, which has been shown to be blocked by PPARγ agonists, leading to their obesity-related effects." (PMID 27142691, 2016).
Obesity (continued). "In obesity a variety of cytokines such as TNFα secreted by adipose tissue can induce the Cdk5 dependent PPARγ phosphorylation." (PMID 27483259, 2016). "In obesity cytokine and high fat diet induced CDK5 mediated phosphorylation of PPARγ is reported to dysregulate expression of a number of genes including adiponectin." (PMID 25143786, 2014). "It is well known that CDK5 activity increases in inflammatory conditions, such as obesity." (PMID 37189440, 2023). "Similarly, dysregulation of gene expression upon phosphorylation of PPARγ on S273 by cyclin-dependent kinase 5 (CDK5) is particularly apparent in the context of obesity." (PMID 32249683, 2020). "Increases in PPARγ posttranslational phosphorylation at serine residues induced by various kinases such as CDK5, extracellular signal-regulated kinase-1/2 and c-Jun N-terminal kinase were reported to be involved in the pathogenesis of insulin resistance, inflammation and obesity." (PMID 28811832, 2017). "As Pparγ upstream factors such as CDK5 are considered as new molecular targets for insulin resistance and other metabolic diseases, mechanism studies of these compounds may provide new molecular targets for obesity and obesity-related metabolic diseases." (PMID 27611793, 2016). "The serine 273 (Ser273) phosphorylation of PPARγ is regulated by cyclin-dependent kinase 5 (CDK5) and extracellular signal-regulated kinase (ERK) and is higher in mouse models of diet-induced obesity." (PMID 40985048, 2025). "Besides being implicated in obesity, CABLES1 could potentially also play a role in the development of diabetes through its role as an adaptor protein for CDK5, which has been shown to control diabetogenic actions of PPARG, a master regulator of adipogenesis and crucial for adipocyte function." (PMID 37555665, 2023). "Furthermore, CDK5 and HSD11B1 are therapeutic targets of preclinical (L-751250) and Phase 1 (AZD8329) drugs for obesity, respectively, and our results provide genetic support for early stage development." (PMID 38167462, 2024). "In 2014 the same authors demonstrated that the phosphorylation of PPARγ-Ser245 by CDK5 did not alter its adipogenic activity but dysregulated a specific set of genes with roles in obesity and diabetes." (PMID 37189440, 2023). "Activated CDK5 can in turn phosphorylate proliferator of peroxisome-activated receptor gamma (PPARG), a master regulator of adipogenesis and adipocyte metabolism, at serine 273 in AT, as seen in diet-induced obesity in mice." (PMID 37555665, 2023). "Of particular current interest is the emerging role of CDK5 in obesity, since PPAR-γ, the essential master regulator of adipogenesis required for mature adipocyte differentiation adipokine production, was recently found to be a major substrate for CDK5-mediated phosphorylation and inactivation." (PMID 29535807, 2018).
Cognitive impairment (31 papers, 2015 to 2026). Abnormal cognition is characterized by deficits in thinking, reasoning, or remembering. "Abortive attempts of neurons to reenter the cell cycle via CDK5 activation causes persistent synaptic loss, neurodegeneration, and AD-like cognitive deficits in mouse models." (PMID 31113950, 2019). "p35 is an activating co-factor of Cyclin-dependent kinase 5 (Cdk5), a protein whose dysfunction has been implicated in a wide-range of neurological disorders including cognitive impairment and disease." (PMID 29867369, 2018). "Cdk5 is also increased in the brains of mild cognitive impairment (MCI) patients, who show a higher risk of AD." (PMID 26317805, 2015). "This study aims to determine whether higher or lower expression of Cdk5 levels in the blood of AD and Mild Cognitive Impairment (MCI) patients is associated with an increased risk of cognitive decline by correlating with Mcl1 level." (PMID 41154594, 2025). "As alterations in neuronal structure underlie cognitive impairment, we tested whether Fingolimod application might prevent the abnormalities in neuronal structure typical of two neurodevelopmental disorders, namely Rett syndrome and Cdk5 deficiency disorder." (PMID 32349283, 2020). "As such, the administration of CDK5 peptide inhibitor reduced tau phosphorylation, thereby protecting against cognitive deficit." (PMID 41513640, 2026). "In turn, p35 binds to and activates CDK5, which phosphorylates tau, leading to its aggregation and, ultimately, cognitive deficit." (PMID 41513640, 2026). "This study takes a significant step forward by screening a library of CDK5 inhibitors for their potential to rescue T2D phenotypes, cognitive impairments, and neurodegeneration in a T2D mouse model induced by a HFD." (PMID 40224020, 2025). "Studies have shown inhibition of hyperactive Cdk5 mitigates intracerebral neurotoxicity in diabetes and attenuates neuronal death and cognitive impairments." (PMID 40224020, 2025). "CDK5 hyperactivation has emerged as a key player in the progression of neurodegeneration, neuroinflammation, and cognitive impairment in various neurological disorders." (PMID 40224020, 2025). "Cyclin-dependent kinase 5 (Cdk5) can be a potent link between T2D and cognitive impairment as this kinase plays a critical role in both disease types." (PMID 40224020, 2025). "The demonstrated rescue effects on muscle strength, anxiety levels, and cognitive impairments underscore the therapeutic potential of Cdk5 inhibitors, offering promising avenues for further research and clinical applications." (PMID 40224020, 2025). "Further fecal microbiota transplantation from normal mice confirmed the role of the gut microbiota in alleviating cognitive deficits by suppressing the activation of the CDK5-involved pathway in TgCRND8 mice." (PMID 39519833, 2024). "Chronic metformin administration was found to ameliorate synaptic malfunctions and cognitive impairment in the amyloid precursor protein (APP)swe/presenilin-1(PS1)DE9 (APP/PS1) mouse model of AD via the inhibition of cyclin-dependent kinase 5 (Cdk5) activity." (PMID 38132442, 2023). "In our investigation of the molecular pathways contributing to cognitive impairments in the T2D mouse model, we have previously documented an association between elevated CDK5 activity and increased p25 generation in the brains of HFD mice, correlating with cognitive deficits." (PMID 40224020, 2025). "Interestingly, CDK5 inhibition can mitigate diabetes-induced neuronal death, potentially offering a therapeutic strategy for diabetes-related cognitive deficits." (PMID 39800748, 2025). "However, screening a Cdk5 inhibitor that efficiently inhibits Cdk5 can help rescue cognitive impairment induced by T2D in diabetic models." (PMID 40224020, 2025).
Cognitive impairment (continued). "CDK5 has been known to be one of the upstream regulators for Drp1 phosphorylation and its activation enhances mitochondrial fission via Drp1 phosphorylation at S616 in chronic ethanol exposure-induced cognitive impairment." (PMID 39390372, 2024). "Thus, acute post-injury Cdk5 inhibition almost completely blocked cognitive impairment in response to rTBI." (PMID 36854738, 2023). "A previous study also demonstrated that inhibition of Cdk5 could attenuate cognitive deficits induced by chronic exposure to ethanol by inhibiting Drp1 phosphorylation at S616." (PMID 38013469, 2023). "Our previous studies also showed that L‐NBP improved cognitive impairment in an APP/PS1transgenic AD mouse model might through inhibitory effects of CDK‐5 and GSK‐3β signaling pathways." (PMID 35445545, 2022). "To test this hypothesis, we used a Cdk5 inhibitor roscovitine, which has been shown to upregulate pSynGAP1 level and improve cognitive impairment." (PMID 33203791, 2020). "We next asked whether REST induction in aged individuals with no cognitive impairment (NCI) but with early AD pathology is associated with repression of CDK5 and GSK3β." (PMID 37919281, 2023). "Cognitive impairment in transgenic AD models is also accompanied by accumulations of phosphorylated tau, which are composed of aberrant forms of phosphorylated tau; indeed, higher activities of GSK3β and Cdk5 kinases result in accumulation of hyperphosphorylated tau in 12-month-old APPswe mice." (PMID 35408893, 2022). "This study evaluated the expression levels of Cdk5 and Mcl1 (Cdk5’s substrate) in blood samples of 61 AD, 55 Mild Cognitive Impairment (MCI), and 57 Geriatric Controls (GC), and explored the in vitro inhibition of Cdk5." (PMID 41154594, 2025). "The cognitive impairment related to spatial learning and memory in HFD mice seemed to be mitigated with the administration of Cdk5 inhibitors BLINK11 and BLINK15." (PMID 40224020, 2025). "We have recently demonstrated that under basal conditions, 5-HT7R physically interacts with CDK5, which results in kinase activation leading to pathological Tau aggregation, impaired LTP, and cognitive deficits in mice." (PMID 38641599, 2024). "Indeed numerous pioneering studies have demonstrated that Cdk5 plays an indispensable role in synaptic plasticity and its deregulation is capable of initiating the early Alzheimer’s synaptic pathology, further resulting in neuronal network dysfunction and cognitive impairment and decline in AD." (PMID 32670025, 2020). "The expression levels of CDK5 and GRM2 were decreased in 5- and 10-month-old 5XFAD mice compared to the controls, providing a mechanistic basis for the synaptic dysfunction and cognitive impairment seen in AD." (PMID 31727875, 2019). "The compound could (i) mitigate cognitive impairments in the Morris water maze and (ii) decrease BACE1, SK3β activity, p25/CDK5, neuroinflammation, soluble and insoluble Aβ, Aβ, plaques and tau pathologies." (PMID 29243055, 2018). "We observed that KXS upregulated AKT phosphorylation, suppressed GSK3β and CDK5 activation, and inhibited the TLR4/MyD88/NF-κB signaling pathway to attenuate Tau hyperphosphorylation and neuroinflammation, thus suppressing neuronal apoptosis and improving the cognitive impairment of aged SAMP8 mice." (PMID 35303280, 2022).
lung cancer (31 papers, 2010 to 2025). A malignant neoplasm involving the lung. "Deficiency of CDK5 or treatment with Roscovitine results in the inhibited proliferation of lung cancer cells [27,]." (PMID 37332205, 2023). "In lung cancer, high CDK5 mRNA expression has been associated with survival, and protein expression is associated with numerous clinicopathological criteria associated with a poor prognosis." (PMID 32352232, 2020). "Blocking CDK5 activity results in failed cytoskeletal remodelling in lung cancer cells, causing them to lose the cell polarity and decline in cellular mobility." (PMID 33396266, 2020). "Higher positive rate of CDK5 was associated with several clinicopathological parameters, which are representative of the progression and deterioration of lung cancer." (PMID 26860827, 2016). "A study of Korean population shows that CDK5 promoter polymorphisms contribute to the genetic susceptibility to lung cancer." (PMID 26860827, 2016). "An elevated expression of CDK5 and p35 in lung cancer cells is associated with enhanced lung cancer cell migration and invasion." (PMID 26690371, 2015). "Single nucleotide polymorphisms (SNPs) in the promoter region of the cdk5 gene have been linked to increased risk for lung cancer." (PMID 25625291, 2015). "Given that the expression of CDK5 is increased in all lung malignancies, and that higher expression of CDK5 in patients with lung cancer is associated with a poorer prognosis, CDK5 inhibitors could be used for treating both NSCLC and SCLC." (PMID 37332205, 2023). "Furthermore, the association between high CDK5 expression and poor prognosis has showed in other human malignancies, such as pancreatic cancer, lung cancer, thyroid carcinoma." (PMID 31311512, 2019). "Therefore, the specific intervention of CRMP2 phosphorylation in lung cancer may be a consequence of its characteristic genetic signature and Cdk5 mutational status." (PMID 34680167, 2021). "Furthermore, we conducted ROC curve to evaluate the diagnostic significance of CDK5 in lung cancer." (PMID 26860827, 2016). "The clinical and functional significance of the LIMK1/CDK5‐Wnt/β‐catenin axis was also verified in esophageal adenocarcinoma, gastric cancer, and lung cancer." (PMID 40476449, 2025). "Western blot analysis of human gastric cancer and lung cancer specimens confirmed that LIMK1/CDK5 protein expression was significantly increased in primary tumors and further enhanced in matched metastatic tumor tissues compared to adjacent normal tissues." (PMID 40476449, 2025). "This is in good accordance with recent studies, which suggest that CDK5 attenuates the Hippo pathway in melanoma and lung cancer." (PMID 39739588, 2025). "Paradoxically, CDK5 can also promote the tumor-suppressing functions of Deleted in Liver Cancer 1 (DLC1) in lung cancer." (PMID 37993880, 2023). "CDK5 drives lung cancer radioresistance mainly by activating Hippo-TAZ signaling; however, the precise molecular mechanism was not delineated." (PMID 37993880, 2023). "CDK5 was shown to transcriptionally upregulate PD-L1 in medulloblastoma and stabilize it in lung cancer, both allowing tumor immunity." (PMID 37993880, 2023). "Achaete-scute homolog-1 (hASH1 aka human ASH1), a basic helix-loop-helix transcription factor, also acts as an upstream regulator of CDK5 activity in lung cancer." (PMID 37993880, 2023). "In lung cancer, Cdk5 regulates tumor suppressor genes, cytoskeletal remodeling, and immune checkpoints." (PMID 34680167, 2021). "In lung cancer, CDK5 promotes the tumour’s progression by inhibiting the tumour-suppressive function of bridging integrator 1 (BIN1)." (PMID 33396266, 2020). "CDK5 upregulation has been associated with a variety of cancers such as colorectal cancer (CRC), lung cancer, and nasopharyngeal cancer (NPC)." (PMID 33396266, 2020).